ALB (albumin)
Diseases named in the same sentence as ALB in open-access papers (continued):
Sharing a sentence is not in itself a finding about the gene and the disease.
liver dysfunction (continued). "Unlike other scoring criteria, AIMS65 incorporates albumin and INR, which are important markers of systemic illness and liver dysfunction, which may explain the association of AIMS65 with mortality." (PMID 41404246, 2025). "Additionally, we adjusted our findings for postoperative MELD score, which shows that low albumin values are not solely influenced by postoperative liver dysfunction and impaired synthesis after HTX." (PMID 38230700, 2024). "The similar outcomes exhibited suggest that the reduction in ALB levels may be due to the inhibitory effects of FEN on hepatic ALB synthesis, or the need to meet immediate energy demands for recovery from toxic stress or liver dysfunction." (PMID 39337314, 2024). "Relations between albumin and markers of liver integrity [e.g., aspartate transaminase (AST)] and blood status (e.g., hemoglobin, red blood cell count, red cell distribution width) suggest that in this sample, albumin reflects both liver dysfunction and hematological abnormalities." (PMID 38260299, 2024). "We found low serum albumin without a corresponding proteinuria or liver dysfunction." (PMID 38715992, 2024). "Notably, all these associations were specific to the direction (high or low) indicative of potential liver dysfunction: low ALT, AST, and GGT and high albumin did not display any association." (PMID 34234104, 2021). "In this study, liver biopsies were not performed (absence of increased cytopathic markers of liver toxicity, e.g., ALT), however, a lower level of albumin and exosomal miR-122 in the absence of renal and enteric signs, suggests liver dysfunction rather than liver damage." (PMID 31936232, 2020). "We examined creatinine, urea, AST, ALT, ALP, albumin, total protein, and indirect and total bilirubin levels to determine whether SLO treatments caused any kidney and liver dysfunctions or not." (PMID 33149751, 2020). "However, no cytotoxic changes to hepatocytes or changes in blood markers associated with liver dysfunction such as increased total protein, total bilirubin or liver enzymes (ALT, AST, and ALP), or reduced albumin, were observed, indicating no harm was imposed on the liver." (PMID 34249709, 2021). "In relation to non-standard-of-care biomarkers and indices of liver dysfunction, those who died had higher serum NT-proBNP, serum AST/ALT, serum hyaluronic acid and serum alpha-2 macroglobulin, but a lower serum albumin." (PMID 39402659, 2024). "In relation to non-standard-of-care biomarkers and indices of liver dysfunction, those who died had higher serum hsCRP, serum NT-proBNP, serum AST/ALT, serum haptoglobin, serum hyaluronic acid and serum alpha-2 macroglobulin, but a lower serum, albumin." (PMID 39402659, 2024). "Therefore, in the current study, the linear increase of cholesterol, albumin, and PON in the blood of calves does not suggest a liver dysfunction even during 2 wk of age when the fecal score was maximal." (PMID 29373601, 2018). "Although albumin levels are slightly above normal values in some patients, the normal values for ALT (alanine transaminase) and AST, together with the lack of clinical signs and no anaemnestic data for hepatitis excludes liver dysfunction." (PMID 27288508, 2016).
Hyperglycemia (225 papers, 2006 to 2026). An increased concentration of glucose in the blood. "The associations between stress hyperglycemia, albumin levels,and cardiovascular prognosis underscore the importance of comprehensive metabolicassessment in ACS patients." (PMID 40351679, 2025). "Third, this model helps identify a high-risk phenotype characterized by hyperglycemia–low serum albumin–inflammation." (PMID 41280395, 2025). "Low albumin and hyperglycemia close to death remained strongly associated with reduced survival, reinforcing the importance of routine metabolic monitoring throughout follow-up." (PMID 41020480, 2025). "Benign hyperglycemia is a common physiological feature of birds, and the development of mechanisms of resistance to albumin glycation appears to be inextricably linked to their evolution." (PMID 38542178, 2024). "Glycated albumin has been considered to reflect postprandial hyperglycaemia and glucose excursion, and postprandial hyperglycaemia was significantly associated with an increased risk of AD in virtue of oxidative stress." (PMID 37483119, 2023). "Benign hyperglycemia is a common physiological feature of birds, and the development of mechanisms to resist albumin glycation is apparently inextricably linked with their evolution." (PMID 34638659, 2021). "Lithium therapy significantly prevented body weight loss, hyperglycemia and urinary excretion of albumin and NGAL, preserved glomerular expression of SYNPO, and diminished renal expression of NGAL, suggesting a beneficial effect against the STZ injury." (PMID 33478120, 2021). "GA level is apparently higher in relation to hyperglycemia in CLD patients due to the prolonged half-life of serum albumin caused by reduced capacity for albumin synthesis." (PMID 29614124, 2018). "Both acute hyperglycemia and chronic hyperglycemia induce shedding of the glycocalyx, contributing to endothelia dysfunction and loss of albumin." (PMID 25887223, 2015). "In this study, hyperglycemia-induced podocyte injury is demonstrated as urine albumin leakage, foot process effacement and loss of podocyte markers, podocin and WT1." (PMID 22848482, 2012). "It has been suggested that glycated albumin (GA) is associated with the risk of complications in diabetic patients, and is used as a marker of hyperglycemia." (PMID 21470398, 2011). "Subgroup analysis demonstrates that age, gender, neutrophil count, red blood cell count, albumin, time to surgery, and surgical duration exhibit interactive effects on the association between preoperative persistent hyperglycemia and POD (interaction p < 0.05)." (PMID 38977983, 2024). "Furthermore, male sex, smoking, high systolic BP, high BMI, hyperglycemia, a high level of total cholesterol, low levels of hemoglobin and albumin, and low eGFR were associated with abnormal echocardiographic findings in the patients with CKD and DM." (PMID 29581872, 2018). "The importance of infection, azotemia, hyperglycemia, and reduced albumin levels as risk factors for the development of diaphragm weakness in mechanically ventilated patients, however, is unknown." (PMID 23786764, 2013). "Since hyperglycemia decreases regenerative potential of the myocardium, we excluded patients and controls with hyperglycemic random blood sugar levels from our investigation, to evaluate the association of albumin, fibrinogen and modified proteins with ACS independently from hyperglycemia." (PMID 35881574, 2022). "In addition, data suggest that azotemia, hyperglycemia, and low systemic albumin levels are risk factors for prolonged mechanical ventilation and could theoretically be associated with the development of respiratory muscle weakness." (PMID 23786764, 2013). "Upon admission, his blood glucose level was 30.21 mmol/L, and glycated albumin was 33.1% (reference range: 4%–6%), indicating long-term hyperglycemia." (PMID 40927698, 2025).
Hyperglycemia (continued). "Albumin and severe hyperglycaemia showed an important effect, with the largest difference occurring in patients with severe hyperglycaemia and normal albumin levels." (PMID 41446043, 2025). "The pathogenesis of DKD is related to multiple factors, including inflammatory cascade reactions, oxidative imbalance, albumin overload, and metabolic disorders such as persistent hyperglycemia." (PMID 40509901, 2025). "Patients with severe hyperglycaemia and normal albumin had a mean difference (95% LoA) of −1.85 mmol/L (4.78)." (PMID 41446043, 2025). "In cases of hyperglycaemia-affecting podocytes, there is an alteration in nephrin regulation, resulting in nephrinuria, particularly observed in patients with normal albumin levels." (PMID 40149650, 2025). "In hyperglycemia, the proportion of somechemical modifications increases (such as glycosylation and cysteinylation),leading to decreased levels of albumin." (PMID 40351679, 2025). "In STZ-induced DN rats, DIO administration (20 mg/kg, 8 weeks) significantly reduced hyperglycemia, serum creatinine and urinary albumin, concurrently attenuating renal histopathological lesions." (PMID 40458807, 2025). "The NFS includes variables such as age, body mass index (BMI), hyperglycemia, platelet count, albumin, and AST/ALT ratio, and is specifically validated for NAFLD." (PMID 39559436, 2024). "Logistic regression analyses showed that seven factors were associated with FI, including age, GCS scores, APACHE II scores, route of feeding, mechanical ventilation, hyperglycemia, and serum albumin." (PMID 39507904, 2024). "Articles using triglyceride glucose index at admission and glucose to glycated albumin ratio to measure acute hyperglycemia were excluded." (PMID 39247028, 2024). "After a remarkable reduction in hyperglycemia following islets transplantation, kidney function improved compared to the diabetic control group, which increased serum albumin, and decreased BUN concentration." (PMID 38724923, 2024). "Taken together, hyperglycemia or low albumin means a higher FAR, which is theoretically correlated with poor outcomes." (PMID 39064013, 2024). "Albumin excretion AUC was significantly higher in diabetic LPD offspring than diabetic NPD offspring following 18 weeks of hyperglycemia (p < 0.05)." (PMID 36695822, 2023). "It has been reported that STZ-treated mice exhibit hyperglycemia, hyperfiltration, and high urinary albumin levels compared with untreated mice and that these aspects are improved in Sglt2-knockout mice and by SGLT2 inhibitors." (PMID 36787192, 2023). "Urine specific gravity was 1.011 and blood analysis displayed azotaemia, hyperphosphatemia, hyperglycaemia and hyponatremia, together with increase in albumin and globulin consistent with mild dehydration." (PMID 37057032, 2023). "LPD‐diabetic mice showed only mild increases in albumin excretion and glomerular pathology despite having severe hyperglycemia over 18 weeks." (PMID 36695822, 2023). "Urinary albumin excretion, glomerular size, and podometrics were assessed following 18 weeks of hyperglycemia." (PMID 36695822, 2023). "A study showed that hyperglycemia promotes albumin penetrance by upregulating the ROS/Src/Cav-1 pathway and downregulating the AMPK/Cav-1 pathway." (PMID 38259279, 2023). "Nevertheless, one recent study used the ratio of fasting plasma glucose (FPG) to glycated albumin (GA) to assess stress hyperglycemia considering the background glucose level before the onset of the acute event." (PMID 36944934, 2023). "Salidroside block hyperglycemia-induced albumin cell-penetration by a mechanism achieved through the dual action of antioxidant effects and activation of AMPK, thus exerting a palliative effect on proteinuria." (PMID 38259279, 2023). "Human albumin is an extracellular multifunctional protein that has recently become a biomarker of hyperglycemia." (PMID 36913679, 2023).
Hyperglycemia (continued). "Stress hyperglycemia was defined by the glucose/glycated albumin (GA) ratio, calculated as admission fasting plasma glucose divided by GA." (PMID 36944934, 2023). "Treatment with tangeretin reduced hyperglycemia-induced renal podocyte injury and recovered renal albumin excretion in db/db mice." (PMID 36771740, 2023). "Diabetic animals showed hyperglycemia, reduced body weight gain, polyuria and increased urinary albumin." (PMID 35984863, 2022). "Our results indicate that in WT mice, kidneys exposed to hyperglycemia plus HTN had greater glomerular injury and urinary albumin excretion than kidneys exposed to only hyperglycemia or HTN." (PMID 34866402, 2022). "In previous reports, acute glycemic changes in isolated postprandial hyperglycemia form the sharp glycemic spikes leading to endothelial dysfunction and urine albumin excretion." (PMID 36060962, 2022). "proved that the function of proximal tubule handling of albumin in hyperglycemia state is abnormal, resulting in albumin-derived peptinuria, excreted in the nephrotic range, which is not related to the change of glomerular capillary wall permeability." (PMID 35837297, 2022). "We found that, in diabetic mice, subcutaneous midazolam treatment for 6 weeks attenuated hyperglycemia-induced elevation in urine albumin/creatinine ratios." (PMID 35054938, 2022). "Persistent hyperglycemia destroys the glomerular filtration barrier, leading to glomerular structural damage, resulting in urinary protein or albumin leakage, and which, in turn further aggravates the progression of DKD." (PMID 34980163, 2022). "Hyperglycemia induces hyperfiltration and morphological alterations in the kidneys, which then leads to excessive excretion of albumin in the urine (albuminuria), damage to the podocytes, and loss of the surface area of the kidney." (PMID 33789608, 2021). "In comparison, glycated albumin (GA), a ketoamine formed by binding of albumin and glucose, more accurately reflects short-term changes in plasma glucose and postprandial plasma hyperglycemia (PPH)." (PMID 33915834, 2021). "In recent years, a large number of studies have found many differentially expressed proteins in the state of hyperglycemia, including bone morphogenetic protein 7, lactoferrin, albumin, cathepsin D, etc.." (PMID 34957219, 2021). "Changes of circulating concentration and structural modification of albumin induced by hyperglycemia or free radicals damage its antioxidant effects, which eventually lead to increased oxidative stress." (PMID 34526116, 2021). "In T2DM, hyperglycemia leads to glycation of albumin and other plasma proteins to generate soluble β-rich protein aggregates as the main player in developing diabetic complications which finally form insoluble amyloid fibrils." (PMID 32612182, 2020). "To determine the effect of TS on hyperglycemia-induced vascular leakage in the diabetic retina, we assessed albumin extravasation after perfusion in retinas of control, DB and DB + TS rats by Western blotting." (PMID 32660051, 2020). "For example, RTN1A over-expression is sufficient to induce ER stress and apoptosis in renal cells, whereas reduced expression of RTN1A attenuates ER stress induced by tunicamycin, albumin, and hyperglycemia." (PMID 32011236, 2020). "NFS is based on six variables including age, BMI, hyperglycemia, platelet count, albumin and AST/ALT ratio." (PMID 32481684, 2020). "In summary, CD36 mediates apoptosis of tubular cells induced by hyperglycemia, glycated albumin, FAs, or oxHDL, while hyperglycemia, albumin, AOPPs, or oxLDL promote interstitial fibrosis by EMT, the secretion of ECM proteins, and TGF-β1 and inflammation." (PMID 32796572, 2020). "At 8 weeks after administration, renal injury, including hyperglycemia, hyperlipidemia, increased urinary albumin excretion, ECM accumulation, and a fractional mesangial area, was dramatically attenuated." (PMID 31871464, 2019).
Hyperglycemia (continued). "Prognosis of GBS patients with hyperglycemia(p=0.002), hyponatremia that serum sodium level lower than 135mmol/L (p=0.020), and serum albumin level lower than 40g/L(p=0.005), were worse." (PMID 32922875, 2018). "Treatment of Akita mice with insulin implants for 20 weeks normalized hyperglycemia and decreased urinary albumin excretion." (PMID 29641741, 2018). "Treatment with M. balsamina, however, was shown to increase excretion of urea and albumin in STZ-diabetic rats possibly via the amelioration of hyperglycaemia." (PMID 30009183, 2018). "After induction of hyperglycemia and tMCAO, we examined 4 treatment groups: 1) bovine serum albumin (BSA), 2) prHSP27, 3) tPA, 4) tPA plus prHSP27." (PMID 29795667, 2018). "On the other hand, hyperglycemia significantly altered the levels of serum albumin, BUN and CK in STZ intoxicated group." (PMID 28878669, 2017). "Hyperglycemia induces the formation of advanced glycation end products (AGEs) that binds with albumin protein and significantly reduces its level." (PMID 28878669, 2017). "Administration of MSC and MSC-CM reduced urine albumin secretion despite unattenuated hyperglycemia in diabetic mice." (PMID 27721418, 2016). "Serum albumin concentration is a promising prognostic marker in hospitalized diabetic individuals with acute hyperglycemia." (PMID 27504458, 2016). "Hyperglycemia- (HG-)Amadori-glycated albumin- (AGA-) induced activation of microglia and monocytes and their adherence to retinal vascular endothelial cells contribute to retinal inflammation leading to diabetic retinopathy (DR)." (PMID 25815338, 2015). "We will also include recent data focusing on glycated albumin and its link to hyperglycemia-induced oxidative damage in adipocytes." (PMID 25878764, 2015). "This obvious circumstance would make a priori glycosylated albumin a more acceptable indicator of hyperglycemia." (PMID 26213657, 2015). "In fact, glycosylated albumin has been proposed as an indicator of maintained hyperglycemia (i.e., exposure of plasma proteins to higher aldose levels for long periods)." (PMID 26213657, 2015). "To evaluate glomerular hyperfiltration induced by hyperglycemia in diabetic rats, we measured 24-hour urinary albumin excretion (UAE)." (PMID 24812636, 2014). "The incomplete normalization of albumin excretion in the diabetic rats receiving test compound is consistent with the persistent and marked hyperglycemia in these animals." (PMID 24303153, 2013). "It is easy to calculate from routine parameters (age, hyperglycaemia, BMI, platelet count, albumin, and AST/ALT ratio) and has been independently validated in populations of various ethnicities, BMI, and diabetic status." (PMID 23209914, 2012). "Exercise reduced urinary levels of albumin and also maintained the number of podocytes in the exercised KK-Ay mice independently of improvements of overweight and hyperglycemia, although moderate-intensity exercise increased expression of HIF-1α." (PMID 22899901, 2012). "GA is now widely regarded as a sufficiently accurate reflection of short-term hyperglycemia control (two-week periods) because ALB has a circulating half-life of about 17 days." (PMID 23209844, 2012). "The NAFLD fibrosis score (NFS) is generated using a panel including six variables of age, hyperglycaemia, BMI, platelet count, albumin, and AST/ALT ratio (AAR), which was created using a large cohort of biopsy-proven NAFLD patients." (PMID 22110476, 2012). "In normal human serum, approximately 6 to 10% of the albumin is glycated, while in hyperglycemia, this proportion typically increases two- to three- fold." (PMID 21966363, 2011). "First, the so called "Simple Test" for fibrosis in NAFLD is a relatively easy to use panel that includes age, hyperglycemia, body mass index, platelet count, albumin, and AST/ALT." (PMID 21849046, 2011).